CD5L (CD5 molecule like)
Diseases named in the same sentence as CD5L in open-access papers (continued):
Sharing a sentence is not in itself a finding about the gene and the disease.
liver cancer (6 papers, 2019 to 2023). An epithelial or non-epithelial malignant neoplasm that arises from the liver. "T cell-related RNAs EOMES, CST7, CD5L, has-miR-23b-3p, and has-miR-23a-3p may be associated with the prognosis of liver cancer." (PMID 34980144, 2022). "HSPA5 is regulated by CD5L and promotes the proliferation of liver cancer cells, playing an antiapoptotic role." (PMID 36982218, 2023). "The survival analysis showed that the T cell-related genes EOMES, CST7, CD5L, and EMR2 were associated with the prognosis of liver cancer." (PMID 34980144, 2022). "Upregulated expression of T cell-related genes including EOMES, CST7, and CD5L indicated the favorable prognosis of liver cancer." (PMID 34980144, 2022). "The survival analysis revealed that upregulated expression of T cell-related genes including EOMES, CST7, and CD5L indicated the favorable prognosis of liver cancer." (PMID 34980144, 2022). "We found COLEC10, GPAA1, CD5L, NCSTN, SNX27, GOLPH3L, and HIST2H2AC genes were associated with worst OS (HR < 1) in female liver cancer patients." (PMID 31216110, 2019). "In addition, there were 30 CD8 T cell-related genes associated with liver cancer prognosis [e.g., CD5 molecules like CD5L, EOMES, and CST7]." (PMID 34980144, 2022). "However, in healthy individuals and in cirrhotic patients with liver cancer, IgM and CD5L levels are positively correlated." (PMID 35330909, 2022). "Thus, we speculate that CST7 and CD5L contribute to liver cancer progression." (PMID 34980144, 2022). "CD5L (CD5 molecule‐like) is a secreted glycoprotein that participates in cancer, promotes proliferation and inhibits cisplatin‐induced apoptosis in liver cancer." (PMID 35441741, 2022).
liver disease (6 papers, 2009 to 2025). "Overall, our results reinforce the notion that circulating CD5L (in EVs and total plasma) is strongly associated with the severity of liver disease." (PMID 35330909, 2022). "In order to address this issue, we developed and characterized a novel sandwich enzyme‐linked immunosorbent assay (ELISA) for human CD5L, assessed CD5L concentrations in serum samples from a circadian profile study, from patients with liver disease and women during pregnancy." (PMID 39345206, 2025). "Regarding the effect of CD5L in the liver disease, it has been proved that CD5L plasma levels are upregulated in patients with liver damage." (PMID 34750342, 2021). "And CD5L, a key regulator of lipid synthesis, was also identified as a possible marker in liver disease (Gangadharan, Antrobus, Dwek, & Zitzmann, 2007)." (PMID 31056863, 2019). "Using the MELD and CHILD‐Pugh scores as indices of severity of liver dysfunction and mortality risk, respectively, no direct relationship between these liver disease parameters and serum CD5L concentration was detected." (PMID 39345206, 2025). "Circadian effects and the impact of liver disease on serum CD5L concentrations were assessed." (PMID 39345206, 2025). "We previously hypothesized that the increase in CD5L during liver disease may be an adaptive response to liver damage and fibrosis that seeks to counteract inflammatory signaling." (PMID 35330909, 2022). "However, considering the anti-tumor activities in HCC and its pleiotropic functions in liver diseases, further study is need to investigate the specific roles of CD5L in HCC." (PMID 36494696, 2022). "Moreover, our notion on little influence of age and sex on circulating CD5L concentrations has been derived from patients with liver disease only, and is in need of replication in other groups of healthy and diseased male and female subjects spanning a wider age range." (PMID 39345206, 2025). "Moreover, trimester‐specific data on the variation of CD5L during pregnancy are not yet at hand, it is unknown whether it qualifies as biomarker in women under T4 treatment, and in particular whether it provides diagnostic information in pregnant women with thyroid or hepatic disease." (PMID 39345206, 2025). "Similarly, no obvious dependence on age of serum CD5L concentrations was noted in the patients with liver disease." (PMID 39345206, 2025). "However, it seems likely that covariates other than TH also influence serum CD5L levels, and it is not known whether endocrine regulation of CD5L by TH takes precedence over, for example, circadian, liver disease‐related, or pregnancy‐related effects." (PMID 39345206, 2025).
Sepsis (5 papers, 2021 to 2025). Sepsis is defined as life-threatening organ dysfunction caused by a dysregulated host response to infection. "Here, we demonstrate the utility of CD5L for treating experimental sepsis caused by cecal ligation and puncture (CLP)." (PMID 38750020, 2024). "Next, we evaluated the potential of CD5L in controlling inflammation caused by in vivo administration of LPS, in a model conventionally termed sterile sepsis." (PMID 38750020, 2024). "Other transcripts upregulated in CD5L− peritoneal cells, including Osm, Il18bp, Ripk1, Nub1, Tlr2, Stat1, Irf1, Nfkb1, Pik3r5, or their coding proteins, were already associated with sepsis severity." (PMID 38750020, 2024). "Indeed, recent studies reported that high concentrations of CD5L strongly predict 30-day mortality risk in individuals with bacterial pneumonia and 28-day mortality in adults and pediatric individuals with sepsis." (PMID 34629330, 2021). "This study investigates the role of the Apoptosis Inhibitor of Macrophages (AIM), also known as CD5L, as a potential prognostic biomarker and therapeutic target in sepsis." (PMID 41262245, 2025). "A recent analysis on the potential health-supporting function of CD5L was conducted in an experimental model of sepsis indicating positive effects on survival with CD5L supplementation." (PMID 40227412, 2025). "Intravenous administration of recombinant CD5L (rCD5L) in immunocompetent C57BL/6 wild-type (WT) mice significantly ameliorates measures of disease in the setting of high-grade CLP-induced sepsis." (PMID 38750020, 2024). "Within sepsis patients, serum CD5L levels were significantly higher in patients with septic shock compared to patients without shock, and in patients with bacteremia compared with those without bacteremia." (PMID 38750020, 2024). "Authors explore the utility of CD5L for treating experimental sepsis." (PMID 38750020, 2024). "The accumulated evidence strongly suggests that CD5L may have a pivotal role in infection and is likely involved in sepsis." (PMID 38750020, 2024). "This distinction in the form and enrichment levels of CD5L during therapeutic administration may contribute significantly to its outstanding therapeutic efficacy in experimental sepsis, suggesting promising avenues for exploration in human medicine." (PMID 38750020, 2024). "In addition, we observed broad interactions between KC_Cxcl10/KC_Cd5l and Hep/Endo through chemokines (including Cxc and Cc subfamilies) and the receptor Ackr1 in response to sepsis." (PMID 37808269, 2023). "Rather than a mere transient increase in total CD5L as a consequence of therapy, it is the free form in which rCD5L enters the system that may elucidate its exceptional therapeutic efficacy in treating experimental sepsis." (PMID 38750020, 2024).
acute kidney injury (4 papers, 2017 to 2022). Sudden and sustained deterioration of the kidney function characterized by decreased glomerular filtration rate, increased serum creatinine or oliguria. "Remarkably, significantly lower levels of CD5L were observed in patients with either circulatory, brain or respiratory failure, without apparent changes in their levels in patients with liver, coagulation or renal failure." (PMID 35330909, 2022).
Autoimmunity (4 papers, 2019 to 2025). The occurrence of an immune reaction against the organism's own cells or tissues. "In fact, some of the proteins we identified have also been associated with autoimmune conditions, such as S100A9 and rheumatoid arthritis, CD5L and systemic lupus erythematosus." (PMID 40215752, 2025). "CD5L influences the plasticity of Th17 cells, which play a role in autoimmunity." (PMID 33920819, 2021). "Furthermore, loss of CD5L converted non-pathogenic Th17 cells into pathogenic cells that induced autoimmunity." (PMID 33920819, 2021).
fibrosis (4 papers, 2009 to 2019). the formation of excess fibrous connective tissue in an organ or tissue in a reparative or reactive process. "While this falls short of the accuracy of the European Liver Fibrosis (ELF) panel, recently validated in NAFLD patients and having an AUC of 0.9 for advanced fibrosis, CD5L is a single biomarker whose performance in conjunction with others may yet improve." (PMID 19656391, 2009).
liver cirrhosis (4 papers, 2017 to 2025). "Taken together, these results indicate a loss of circulating EVs at all stages of liver cirrhosis and a differential content in CD5L as the disease progressed." (PMID 35330909, 2022). "Together, these findings suggest that development of extrahepatic organ failures (i.e. circulatory, brain or respiratory failures) in patients with well advanced and decompensated liver cirrhosis could be associated with defective circulating CD5L concentrations." (PMID 35330909, 2022). "Collectively, the data indicate no consistent impact of sex, age, or impaired liver function on serum CD5L concentrations in the patients with liver cirrhosis." (PMID 39345206, 2025). "To characterize the CD5L content of EVs, we purified EVs by SEC from total plasma from HS (n=6) and patients with liver cirrhosis at different stages of severity [CC (n=6), AD (n=11) and ACLF (n=11)]." (PMID 35330909, 2022).
liver fibrosis (4 papers, 2009 to 2025). "Recent studies have shown that, in liver pathology, CD5L levels are elevated in patients with hepatic injury and are associated with hepatic fibrosis and cancer." (PMID 40647574, 2025). "LyC6low monocytes have been proposed to orchestrate the regression of liver fibrosis and, interestingly, to overexpress Cd5l." (PMID 33920819, 2021). "Regarding the role of CD5L in hepatic fibrosis, studies by our group using an in vivo model of moderate fibrosis induced by the hepatotoxic compound carbon tetrachloride (CCl4) demonstrated that administration of rCD5L had a protective effect on liver injury and lowered the inflammatory response." (PMID 33920819, 2021). "Elevation of CD5L was documented in patients with systemic lupus erythematosus, ARDS, chronic kidney disease, cardiovascular events, liver fibrosis, etc.." (PMID 36556186, 2022). "The notably higher AUC values of CD5L and TGFβ1- in comparison with APRI- suggest that while APRI can serve as a valuable screening tool for liver fibrosis, there may be limitations in its specificity compared to more sensitive markers." (PMID 40647574, 2025).
systemic lupus erythematosus (4 papers, 2014 to 2025). An autoimmune multi-organ disease typically associated with vasculopathy and autoantibody production. "Recently, circulating CD5 levels were shown to be increased in RA and systemic lupus erythematosus, and currently we have confirmed the elevation of its ligand, CD5L, in PsA SF." (PMID 25097465, 2014).
chronic kidney disease (3 papers, 2021 to 2025). Impairment of the renal function secondary to chronic kidney damage persisting for three or more months. "In chronic kidney disease, serum CD5L is associated with cardiovascular events and all‐cause mortality." (PMID 39345206, 2025).
COVID-19 (3 papers, 2021 to 2025). A disease caused by infection with severe acute respiratory syndrome coronavirus 2. "Unlike early time points, the radar plot shows similar average protein abundances across IVIG-treated subjects, COVID-19 controls, and healthy donors, with CD5L as the only protein showing a significant difference compared to COVID-19 controls." (PMID 40821834, 2025). "Other proteins that could potentially be employed in therapies against COVID-19 but that so far have not been associated with the disease are CD5L, VDBP, A1BG, C4BPA, PGLYRP2, SERPINC1, and APOH." (PMID 37371071, 2023). "In addition, other proteins that could be employed in therapies against COVID-19 but that so far have not been associated with the disease are CD5L, VDBP, A1BG, C4BPA, PGLYRP2, SERPINC1, and APOH." (PMID 37371071, 2023). "However, radar plots revealed a clear decrease in the average abundance of several complement proteins in IVIG-treated patients compared to both COVID-19 controls and healthy donors, including C1RL, CFD, CD5L, C8G, and CFHR5." (PMID 40821834, 2025). "A refined linear regression analysis of the proteomic hits (FDR < 0.05) further identified 23 upregulated proteins, of which the top 9 are the same and revealed 2 downregulated proteins in COVID-19+ patient urine, hypoxanthine phosphoribosyltransferase 1 (HPRT1) and CD5 molecule–like (CD5L)." (PMID 34767537, 2021).
lung adenocarcinoma (3 papers, 2021 to 2025). A carcinoma that arises from the lung and is characterized by the presence of malignant glandular epithelial cells. "CD5L overexpression in the alveolar type II epithelial cells (AT II cells) of transgenic mice induced malignant transformation and spontaneous lung adenocarcinoma by inhibiting apoptosis of lung epithelial cells and promoting immune escape." (PMID 34517344, 2021). "For the significant proteins identified in the observational analyses, Agrin (AGRN), CD5 antigen‐like (CD5L), glucosamine‐6‐phosphate isomerase 1 (GNPDA1), integrin beta‐2 (ITGB2) and neuronal‐specific septin‐3 (SEPTIN3) remained associated with lung adenocarcinoma in the two‐sample MR analyses." (PMID 41340014, 2025).
metabolic syndrome (3 papers, 2020 to 2022). A cluster of metabolic risk factors for CARDIOVASCULAR DISEASES and TYPE 2 DIABETES MELLITUS. "Cox proportional hazards models showed that CD5L was an independent predictor of all-cause mortality (HR, 1.22; 95% CI, 1.01–1.48) after adjusting for CV risk factors such as age, sex, diabetes, waist circumference, smoking, systolic blood pressure, dyslipidemia, and CKD stage." (PMID 34629330, 2021). "In our study, we measured inflammatory and anti-inflammatory markers associated with psoriasis and the metabolic syndromes sTLR2, CD5L, and sCD200R1, the levels of which have not been evaluated yet." (PMID 36556186, 2022). "Higher baseline CD5L concentration was associated with increased risk of CVE (HR, 95% CI, 1.17, 1.0–1.36), and all-cause mortality (1.22, 1.01–1.48) after adjusting for age, sex, diabetes, systolic blood pressure, dyslipidemia, waist circumference, smoking, and CKD stage." (PMID 34629330, 2021). "We selected four markers: CRP, sCD200R1, CD5L, and sTLR2; in particular, sCDR2001 has not yet been measured in the context of psoriasis and metabolic syndrome." (PMID 36556186, 2022). "It is possible that although CD5L plays an important role in the pathogenesis of metabolic syndrome, its expression is not significantly induced by this condition alone." (PMID 36556186, 2022).
ovarian carcinoma (3 papers, 2017 to 2023). A malignant neoplasm originating from the surface ovarian epithelium. "Our analysis of an ovarian cancer cohort stratified by resistance or responsiveness to bevacizumab-based therapy demonstrated a correlation between the overexpression of CD5L in tumor endothelial cells and bevacizumab resistance." (PMID 37100807, 2023). "Here, the authors show that in ovarian cancer anti-VEGF inhibitors induce the overexpression of CD5L in endothelial cells through hypoxia-driven PPARy activation and that blocking CD5L can overcome resistance." (PMID 37100807, 2023). "To elucidate the downstream effects of blocking endothelial CD36-mediated CD5L signaling, we obtained an endothelial-specific CD36flox/flox knockout mouse model CD36ffTie2Cre and inoculated the mice with syngeneic murine ovarian cancer ID8-Luc cells." (PMID 37100807, 2023). "In addition, we performed IHC staining for CD5L on a tissue microarray (TMA) consisting of tumor samples from an ovarian cancer cohort." (PMID 37100807, 2023). "To determine the potential clinical relevance of CD5L overexpression, we first interrogated a select cohort of ovarian cancer patients identified as bevacizumab responders versus non-responders." (PMID 37100807, 2023).
psoriasis (3 papers, 2021 to 2022). An autoimmune condition characterized by red, well-delineated plaques with silvery scales that are usually on the extensor surfaces and scalp. "In addition, p19/CD5L could be a good diagnostic marker for autoimmune and inflammatory diseases including multiple sclerosis and possibly psoriasis." (PMID 33664371, 2021). "Psoriasis is also an inducer of CD5L expression, which reflects severity." (PMID 36556186, 2022). "Moreover, p19 targeting would also blockade not only IL-23 but also IL-39 and p19/CD5L, both of which might be involved in worsening psoriasis." (PMID 33664371, 2021).
Stroke (3 papers, 2021 to 2022). Sudden impairment of blood flow to a part of the brain due to occlusion or rupture of an artery to the brain. "The most significantly upregulated genes, including Lpl, Spp1, Cd36, Mmp2, and Mmp19, and the most highly enriched genes, including Cd5l, Mmp3, Mmp12, and Mmp13, indicate a pronounced disturbance in lipid homeostasis in infarcts at 7 weeks after stroke." (PMID 34819339, 2022).
type 2 diabetes (3 papers, 2018 to 2021). "Clinical studies showed that IGFBP-3 is down-regulated in Type 2 Diabetes patients with renal disfunction, and predict future renal decline in people with type 2 diabetes combined with apoA4 and CD5L." (PMID 35002740, 2021). "Recently, of eight candidate biomarkers studied after adjustment for clinical predictors, apolipoprotein A4 (ApoA4), CD5 antigen-like (CD5L), and complement C1q subcomponent subunit B (C1QB) independently predicted rapid decline in eGFR in 345 people with type 2 diabetes." (PMID 29520581, 2018).
atrial fibrillation (2 papers, 2021 to 2023). A disorder characterized by an electrocardiographic finding of a supraventricular arrhythmia characterized by the replacement of consistent P waves by rapid oscillations or fibrillatory waves that vary in size, shape and timing and are accompanied by an irregular ventricular response. "In humans, higher CD5L concentrations on epicardial fat secretome were found in male subjects with heart failure who developed atrial fibrillation." (PMID 34629330, 2021).
diabetes (2 papers, 2021 to 2025). "On the other hand, the absolute log-likelihood value showed that the model, including the interaction between CD5L and diabetes also improved the all-cause mortality model (−424.7 vs. −426.5, p = 0.061)." (PMID 34629330, 2021). "The analysis indicated that those in the 1st quartile of CD5L concentration had a 2.2-fold increased CV mortality risk, even after being adjusted for several other risk factors including low fT3, hypertension, and diabetes." (PMID 40227412, 2025). "The Cox model revealed that the independent predictive variables for CV events were CD5L (HR, 1.19; 95% CI, 1.01–1.41), diabetes (HR, 1.72; 95% CI, 1.09–2.71), age (HR, 1.29; 95% CI, 0.99–1.68), smoking (HR, 2.03; 95% CI, 1.25–3.28) and dialysis (HR, 2.12; 95% CI, 1.17–3.84)." (PMID 34629330, 2021). "As for the biomarkers, the median CD5L concentrations were significantly higher among the participants with diabetes (2,421.2 ng/mL; IQR, 1,899; 3,105) than in those without diabetes (2,206.11ng/mL; IQR, 1,782; 2,802)." (PMID 34629330, 2021).
osteoarthritis (2 papers, 2014 to 2022). A noninflammatory degenerative joint disease occurring chiefly in older persons, characterized by degeneration of the articular cartilage, hypertrophy of bone at the margins and changes in the synovial membrane. "Proteins such as CD5 molecule-like protein (CD5L), soluble scavenger receptor cysteine-rich domain-containing protein (SSC5D), and TTK protein kinase (TTK) were found to be upregulated in the synovial fluid of osteoarthritis patients." (PMID 24393543, 2014).